SLAMF7 (SLAM family member 7)
Diseases named in the same sentence as SLAMF7 in open-access papers (continued):
Sharing a sentence is not in itself a finding about the gene and the disease.
infection (10 papers, 2011 to 2025). The state of being infected such as from the introduction of a foreign agent such as serum, vaccine, antigenic substance or organism. "It suggests also that in human pDCs EAT-2 may interact with SLAMF7 intracellular tyrosine-based switch motifs (ITSMs) upon infection, evoking the direct SAP-independent association of SLAMF7 with EAT-2 that triggers NK cell activation and cytotoxicity." (PMID 40231463, 2025). "Further investigation is needed to unravel pDC SLAMF8 interacting partners, which might also associate with SLAMF7 given their common behavior in these cells upon infection." (PMID 40231463, 2025). "Here, we found that EAT-2 was highly expressed in primary human pDCs, as well as in CAL-1 cells, and stable upon infection with Salmonella and when SLAMF7 or SLAMF8 was downregulated." (PMID 40231463, 2025). "This loss in Th1 cell subset formation coincided with increased frequencies of multiple subsets, including Slamf6-hi, pre-Tfh, ISG, and Slamf7-hi clusters, whereas the Tfh clusters remained similar between infections." (PMID 36255051, 2022). "We identify several transcriptionally distinct states among the Th1, Tfh, and memory-like T cell subsets that form at the peak of infection, including the presence of a previously unrecognized Slamf7+ subset with cytolytic features." (PMID 36255051, 2022). "Although we propose SLAMF7 as a potential therapeutic target in IBD, interference with the SLAMF7 signaling pathway through targeted drugs may increase infection risk." (PMID 40646691, 2025). "Then, we investigated whether SLAMF7 expression specificity correlated with age, sex, infection type, and disease complications." (PMID 36749634, 2023). "In addition to the cytokine and chemokine upregulation observed in this present work, the inflammatory response regulators SLAMF7, RELB, NFKBIZ, NFKBIA, and ZC3H12A were identified, further underlining the strong inflammatory response elicited by PCPEC during to infection." (PMID 33763387, 2021). "We identified the cell surface receptors SLAMF7 and SLAMF8 as key shared players in regulating human plasmacytoid cell response to infection and intracellular bacterial survival." (PMID 40231463, 2025). "Altogether, we establish that human pDCs upregulate the levels of both SLAMF7 and SLAMF8 upon infection with live Salmonella, in a process requiring bacterial viability and prokaryotic RNA recognition." (PMID 40231463, 2025). "We found that in pDCs SLAMF7 and SLAMF8 are coregulated at the protein and mRNA levels in steady state and upon infection or TLR7/8 stimulation." (PMID 40231463, 2025). "This cross talk between SLAMF7 and selected TLR allow for the monocyte/macrophage to mount a concerted robust immune response during infection." (PMID 37420084, 2023). "Our findings identify human SLAMF7 and SLAMF8 as immunoreceptors that trigger human pDC maturation, activation, and proinflammatory cytokine and type I IFN secretion, and promote as well the survival of intracellular bacteria during infection." (PMID 40231463, 2025). "mCherry–B. abortus or –B. melitensis infection highly increased SLAMF7 surface expression at 48 hours post-infection (p.i.)in infected as well as bystander cells, suggesting that soluble factor(s) mediate SLAMF7 overexpression in non-infected cells." (PMID 40231463, 2025). "However, the secondary infection with P. aeruginosa did not upregulate SLAMF7 expression, which was different from what we observed upon the primary infection with P. aeruginosa." (PMID 36749634, 2023).
hematological malignancies (5 papers, 2019 to 2025). "CD19 and the SLAMF7/CS1 receptors are also the subject of therapeutic studies aimed at hematologic malignancies." (PMID 30787933, 2019). "Alternative CAR targets were explored in the treatment of hematological malignancies such as CD3, CD5, CD7, CD33, CD138, SLAMF7 and NKG2D ligands in pursuit of for more effective strategies." (PMID 39633491, 2024).
bacterial infections (3 papers, 2023 to 2025). "Overall, our results unravel essential shared multifaceted roles of SLAMF7 and SLAMF8 in finely tuning human pDC responses to intracellular bacterial infections with potential for future diagnostic and therapeutic applications." (PMID 40231463, 2025). "Thus, in pDCs, which bridge innate to acquired immunity, SLAMF7/8 signaling may constitute a pivotal mechanism for shaping T cell homeostasis and effector function during bacterial infection, as well as for controlling bacterial survival." (PMID 40231463, 2025). "Collectively, these findings indicate that SLAMF7 and SLAMF8 play a positive regulatory role in human pDC responses to bacterial infection by promoting cell activation and proinflammatory cytokine and IFN type I secretion." (PMID 40231463, 2025). "In this study, we demonstrated that SLAMF7 was inducibly expressed on macrophages in response to TLR ligands and bacterial infection and that it interacted with SHIP1 and TRAF6 to attenuate MAPK and NF-κB signaling–mediated proinflammatory cytokine production." (PMID 36749634, 2023).
hematological tumors (2 papers, 2019 to 2025). "The premise arising from this finding is that only hematopoietic cancers that express high levels of SLAMF7 are suitable targets for CD47 blocking therapy." (PMID 30710089, 2019). "In most hematological tumors, FOXP1 expression demonstrated a positive correlation with the expression levels of stimulatory immune genes such as ICOSLG, IL2RA, and HMGB1, and a negative correlation with the expression levels of inhibitory immune genes, such as SLAMF7." (PMID 40672953, 2025).
infectious disease (2 papers, 2023 to 2025). A disorder directly resulting from the presence and activity of a microbial, viral, or parasitic agent in humans. "To date, the definite function and mechanisms of SLAMF7 in infectious disease are still unclear." (PMID 36749634, 2023). "Moreover, SLAMF7 exhibits a negative regulatory effect on inflammation in some infectious diseases." (PMID 36749634, 2023). "Human blood transcriptomic signatures reveal changes in SLAMF7 and SLAMF8 expression levels in a large panel of infectious diseases." (PMID 40231463, 2025). "However, the regulatory function of SLAMF7 during infectious disease has not been clarified." (PMID 36749634, 2023).
SLAMF7 also shares sentences with these, for which no sentence is quoted: leukemia (3 papers); monoclonal gammopathies (3); acute myeloid leukemia (2); bladder cancer (2); inflammatory bowel disease (2); lymphopenia (2); myelodysplastic syndrome (2); myelofibrosis (2); non-Hodgkin lymphoma (2); periodontitis (2); psoriasis (2); Acanthamoeba keratitis (1); adenocarcinoma (1); alveolar rhabdomyosarcoma (1); Alzheimer disease (1); anemia (1); Arthritis (1); B cell NHL (1); bacterial sepsis (1); cervical cancer (1); endotoxemia (1); Fulminant hepatitis (1); head and neck cancer (1); hyperthyroidism (1); IgG4-related disease (1); inflammation (1); inflammatory skin disease (1); interstitial lung disease (1); keratitis (1); lung adenocarcinoma (1).
A further 21 diseases each share a sentence with SLAMF7 in 1 paper.